MC4R (melanocortin 4 receptor)
Diseases named in the same sentence as MC4R in open-access papers (continued):
Sharing a sentence is not in itself a finding about the gene and the disease.
Obesity (continued). "These included genes with established roles in weight regulation (MC4R, GIPR and PCSK1) in addition to new targets, such as GPR75, in which loss-of-function mutations are protective against obesity in humans and mice." (PMID 38575728, 2024). "In terms of “Emotional overeating,” MC4R has been related to obesity by disrupting energy homeostasis and appetite signals." (PMID 38863583, 2024). "This potential is exemplified by setmelanotide, a melanocortin‐4 receptor (MC4R) agonist approved for syndromic obesity." (PMID 39016695, 2024). "Melanocortin-2 receptor accessory protein-2 (MRAP2) is a single transmembrane protein that interacts with MC4R to potentiate it’s signalling, and human mutations in MRAP2 cause obesity." (PMID 39574659, 2024). "One of these genes is the melanocortin-4 receptor (MC4R), and pathogenic variants in MC4R are the most frequent cause of monogenic obesity." (PMID 38567654, 2024). "The overeating, a major driving force behind obesity, is largely coded in genes responsible for regulation of appetite and satiety and MC4R is one of these." (PMID 39203789, 2024). "The oral buccal swab was performed for genotyping of FTO rs9939609, MC4R rs17782313, BDNF rs6265 and genetic risk of obesity was calculated." (PMID 38662725, 2024). "The aim of this study was to analyze the effects of genotypes and haplotypes of the fat mass and obesity-associated (FTO) and melanocortin 4 receptor (MC4R) genes on total body weight loss (TBWL), post-surgery weight, and post-BMI after bariatric surgery." (PMID 38674326, 2024). "SNPs in or near these genes (rs9939609 for FTO, rs17782313 for MC4R, rs6265 for BDNF) are associated increased appetite or energy intake, through which the SNPs are suggested to increase the risk of obesity." (PMID 38662725, 2024). "Many GOOS participants with GNAS variants showed impaired MC4R signalling, suggesting centrally MC4R-mediated hyperphagia leading to obesity." (PMID 39104441, 2024). "These variants mapped to well-established obesity-related genes and loci, such as POC5, MC4R, TMEM18, and the FTO locus." (PMID 38200577, 2024). "The evaluation of deletions and duplications, in regions associated with obesity, is possible by assessing genes LEPR, POMC, SIM1, LEP, MC4R, MC2R, and MC3R, and in the 16p11.2 region by MLPA." (PMID 39458556, 2024). "We found several high-scoring genes for which extensive evidence on their role in obesity already exists, such as MC4R,48,49,50,51BDNF,52,53,54GIPR,55,56,57DGKI,21MTOR,58,59AKT3,60 and LEPR61,62." (PMID 38754426, 2024). "MC4R haploinsufficiency resulted in a phenotypic resemblance for adult-onset obesity that was exacerbated by the consumption of a high-fat diet." (PMID 39741559, 2024). "We calculated the Hardy-Weinberg Equilibrium (HWE) for six genes (CLOCK, GHRL, FTO, LEP, LEPR, MC4R) related to obesity, using genotype frequencies from our dataset." (PMID 39203789, 2024). "Out of the thirty-three genes for which selected genetic variants were reported as significantly associated with obesity, only four genes (LEP, LEPR, POMC, and MC4R) are known to be linked with monogenic obesity." (PMID 39457458, 2024). "Under this condition, POMC-MC4Rflox/flox mice exhibited a remarkably increased body weight from the age of 13-weeks old compared with control mice, accompanied by an increased food intake, indicating that MC4R is involved in developing of obesity." (PMID 38448811, 2024). "Prior to the onset of obesity, the MC4R+/− animals fed the control diet displayed an increased motivation to work for sucrose rewards on all measures of performance." (PMID 39741559, 2024).
Obesity (continued). "Our study, a placebo-controlled randomized trial, delves into the efficacy of specific dietary fiber supplements—glucomannan, inulin, and psyllium—in individuals with obesity-related genetic polymorphisms within genes such as FTO, LEP, LEPR, and MC4R." (PMID 38398881, 2024). "Several of the high-scoring genes (score ≥ 11) are known to be implicated in obesity (such as DGKI [score: 22.8], MC4R [19.6], BDNF [19.6], MTOR [16.8], SH2B1 [14.8], GIPR [14.3], AKT3 [11.6], and LEPR [11.6])." (PMID 38754426, 2024). "Peptides such as the GLP-1 used in T2D care, and melanocortin-4 receptor (MC4R)-specific agonists, prolactin-releasing peptide mimetics, neuropeptides, and apolipoprotein A-I have been shown to possess anti-obesity functions." (PMID 38163110, 2024). "In humans, mutations in MC4R are the most common cause of genetic obesity and the use of setmelanotide, an MC4R agonist, is an effective pharmacotherapy for the treatment of monogenetic and syndromic obesity phenotypes." (PMID 39560101, 2024). "Our index case had hyperphagia and obesity in line with impaired MC4R signalling that we found in vitro." (PMID 39104441, 2024). "Multiple studies have hinted at the potential influence of particular genes linked to obesity risk (i.e., FTO, MC4R, and TMEM18) on GWG, emphasizing the necessity for in-depth investigations into their roles." (PMID 38613027, 2024). "Results from the operant tasks indicate that motivational deficits due to MC4R haploinsufficiency were apparent prior to the onset of obesity and exacerbated by dietary fat consumption after obesity was well established." (PMID 39741559, 2024). "Inactivation of the MC4R gene has been shown to reduce blood pressure independently of obesity in previous studies." (PMID 39104759, 2024). "With MC4R as a promising target for anti-obesity treatments, this investigation of MC4R interaction partners can be of relevance for the development of clinical therapies." (PMID 39062808, 2024). "Genes such as FTO (fat mass and obesity-associated gene), LEP (leptin), MC4R (melanocortin 4 receptor), and PPARG (peroxisome proliferator-activated receptor gamma) are well-established contributors to obesity susceptibility." (PMID 39390356, 2024). "Another study noticed the synergistic impact of other genes such as peroxisome proliferator-activated receptor gamma (PPARγ), FTO, and melanocortin-4 receptor (MC4R)—in the predisposition to overweight and obesity." (PMID 38397196, 2024). "For example, mutations in the genes encoding melanocortin 4 receptor (MC4R), leptin receptor (LEPR), and pro-opiomelanocortin (POMC), result in monogenic obesity." (PMID 38806863, 2024). "It has been found that abnormal hypomethylation of the Avy gene in agouti mice can lead to ectopic protein expression and binding to MC4Rs in the hypothalamus, which destroys the function of the MC4R and results in obesity." (PMID 39200098, 2024). "For example, the fat mass and obesity (FTO) associated gene and the melanocortin 4 receptor (MC4R) gene have been associated with increased body weight and cause obesity; however, it is important to note that genetics alone cannot determine obesity." (PMID 38715796, 2024). "It involved 112 adults with obesity, each with at least one minor allele in the FTO, LEP, LEPR, or MC4R polymorphism." (PMID 38398881, 2024). "Multiple mice studies found that deletion of the MC4R locus produces a significant dysregulation of energy homeostasis, leading to obesity." (PMID 37937009, 2023). "Large-scale genome-wide association studies have shown that genetic variations in BMI-related genes, such as FTO, BDNF, and MC4R, are closely related to obesity." (PMID 37683016, 2023). "Among these, many were well known and had been previously associated with BMI and other obesity traits, such as FTO, MC4R, and other loci." (PMID 36658113, 2023).
Obesity (continued). "The MC4R agonist setmelanotide received FDA approval in 2020 for treating subjects with specific genetic defects upstream of MC4R, resulting in obesity." (PMID 36767008, 2023). "Setmelanotide, an MC4R agonist, was developed for the treatment of severe obesity and appetite control." (PMID 37888071, 2023). "The discovery of FTO has also revealed another strongly associated locus, the melanocortin 4 receptor gene (MC4R), which is associated with weight, fat mass and obesity." (PMID 36717394, 2023). "The genetic screening of 454 families from our cohort, with severe obesity, identified 132 probands (29%) and 13 family members with homozygous or compound heterozygous (likely) pathogenic variants in LEP, LEPR, or MC4R." (PMID 37659411, 2023). "Among all obesity-related genes in the targeted panel, MC4R most frequently expressed variations, which is in accordance with the findings of previous reports." (PMID 37327085, 2023). "Previous studies have also identified numerous genetic loci and gene variants such as FTO, MC4R, ADAMTS9 and GRB14/COBLL1, which have been found to be associated with overweight/obesity and diabetes." (PMID 38089629, 2023). "For example, Melanocortin-4 Receptor (MC4R) is a GPCR involved in food consumption and mutations in this receptor are the most common cause of monogenic obesity." (PMID 37256063, 2023). "We had shown that MC4R and lipocalin-2 gene (LCN2) mutations were detected in 2.42% and 0.84%, respectively, of Spanish children with obesity." (PMID 37025415, 2023). "The “obesity-related” gene group contains MC4R, ATXN2L, GHRL (OR 1.99, P = 8.0×10− 4) and HESX1 (OR 0.23, P = 2.6×10− 3)." (PMID 37292813, 2023). "Supportively, studies in vitro animal models have shown that MC4R knockout mice suffer from severe obesity and the MC4R gene is shared by both mice and humans." (PMID 37531412, 2023). "These include the obesity predisposing FTO (fat mass and obesity associated gene) and MC4R (melanocortin 4 receptor) genes related to food intake control (e.g., appetite, eating behavior) and energy homeostasis regulation." (PMID 36875367, 2023). "In a Turkish study of 105 children with early-onset obesity that screened 41 monogenic obesity genes, around 10.5% of the cases were found to carry genetic variants in the SIM1, POMC, PSCK1, MC4R, and LEPR genes." (PMID 37329217, 2023). "The central importance of MC4R in energy homeostasis has made it a major target for the pharmacotherapy of obesity." (PMID 36692018, 2023). "Co-administration of amylin and an MC4R agonist to rats had a greater effect on weight loss and food intake than treatment with amylin alone, and amylin-induced stimulation of thermogenesis in iBAT was blocked by an MC4R antagonist, indicating that combined treatment may be beneficial in obesity." (PMID 36943057, 2023). "Leptin analogs and MC4R agonists are exclusively used for patients with obesity secondary to congenital/acquired generalized lipodystrophy and POMC deficiency, respectively." (PMID 37937009, 2023). "Given the complex interplay of genetic and environmental factors, as well as the role of the hypothalamus and MC4R in obesity, an intricate approach is essential for understanding and treating this condition." (PMID 38002939, 2023). "Setmelanotide is also being developed in other rare genetic disorders associated with obesity including Bardet-Biedl Syndrome, Alström Syndrome, POMC and other MC4R pathway heterozygous deficiency obesities, and POMC epigenetic disorders." (PMID 36767008, 2023). "A new drug, setmelanotide, an MC4R agonist, shows very promising results in the treatment of this type of obesity." (PMID 37629396, 2023). "Some anti-obesity drugs that act via raising BMR, e.g., thyroid hormone and melanocortin-4 receptor agonists, have been reported to cause cardiovascular side effects." (PMID 37173352, 2023).
Obesity (continued). "Within the context of the emerging connection between primary cilia and energy homeostasis, the observations described here further suggests that all genes controlling localization of MC4R to primary cilia are candidate genes for human obesity." (PMID 36692018, 2023). "Further, we propose α-MSH-induced CRE-driven reporter gene activity be the preferred high-throughput screen to discover potential safe and effective anti-MC4R signaling therapeutics targeting obesity." (PMID 37040537, 2023). "It has been found that dolutegravir (DTG) has a potential for inhibiting melanotropin (MSH) binding to melanocortin 4 receptor (MC4R), which affects leptin signalling responsible for food intake (its deficiency is linked with monogenic obesity)." (PMID 38140673, 2023). "Two studies investigating the moderating effects of urban and rural living environments found a disparity in their effects on obesity and their interactions with MC4R candidate genes in Chinese and Sri Lankan populations." (PMID 37664850, 2023). "The most common cause is mutations in the melanocortin-4 receptor (MC4R) gene and up to 5% of patients with severe obesity during childhood are known to carry the pathogenic mutations causing Mc4r deficiency." (PMID 37957201, 2023). "Our analyses revealed significant associations between SNPs and candidate genes, including the MC4R gene, which showed potential significance and potential effects on appetite and obesity regulation in both AGE100 and BF100 traits." (PMID 37372438, 2023). "Germinal deletion of MRAP2, in Mrap2–/– mice, leads to obesity, although to a lesser extent than that observed in Mc4r–/– mice." (PMID 36692018, 2023). "Taken together, bidirectional manipulations of neurons of the melanocortin pathway (POMC, AgRP, and MC4R neurons) result in severe obesity as predicted while they fail to achieve the expected obesity prevention and reversal phenotypes." (PMID 37069175, 2023). "BBS-related obesity can be partly related to impaired MC4R pathway activity; thus, in 2022, the FDA extended the use of setmelanotide for chronic weight management in adult and pediatric patients ≥ 6 years of age with BBS." (PMID 37571382, 2023). "Highly infrequent single gene mutations (such as LEP, LEPR and POMC) stand for rare cases of monogenic obesity; however, some of them are also related to polygenic obesity (such as MC4R and FTO)." (PMID 36980866, 2023). "The melanocortin-4 receptor (MC4R) gene is involved in regulating energy homeostasis and has been linked to obesity and metabolic consequences." (PMID 37311812, 2023). "Mrap2–/– mice develop severe obesity, although they lack the early-onset hyperphagia of Mc4r–/– mice, which brings into question the extent to which MRAP2 qualitatively and quantitatively interacts with MC4R in vivo." (PMID 36692018, 2023). "In this study, we analyzed effects of MC4R homodimerization on Gq/11 subunit signaling, which appears to be a promising target regarding obesity treatment." (PMID 36009013, 2022). "Genetically speaking, over 600 genetic locus are associated with obesity, and many studies have focused on the LEPR, MC4R, and FTO genes." (PMID 35624438, 2022). "Further obesity-related genes include MC4R, peroxisome proliferator-activated receptor gamma (PPAR-G), and both adipokine-encoding genes (LEP and ADIPOQ)." (PMID 35565885, 2022). "The FTO and the MC4R are typical representatives of obesity, and more evidence supports the relationships between the two loci and stroke events." (PMID 36530622, 2022). "This study aimed to examine association between variant rs17782313 near melanocortin-4 receptor (MC4R) gene and behavioral and hormonal factors then evaluated interactions between variant MC4R rs17782313 with behavioral and hormonal factors on obesity." (PMID 36123585, 2022).
Obesity (continued). "Thus, we posit that it might be possible that the BMI decreasing allele of rs6567160 near MC4R, contributing to its expression levels, has a significant mitigating effect on obesity in conjunction with the homozygous decreasing allele or heterozygous stature of the FTO SNP." (PMID 35508500, 2022). "As a result of these studies, patients with severe obesity and rare SRC-1 variants are now being recruited into phase 2 clinical trials of setmelanotide, an MC4R agonist, licensed for the chronic weight management of POMC and leptin receptor deficiency." (PMID 35137184, 2022). "Although the brain MC4R is an acknowledged target for the treatment of obesity, the development of selective and safe MC4R agonists imposes notable challenges." (PMID 34815532, 2022). "This complexity became more evident when genome-wide association studies (GWAS) began to detect more genetic variants associated with obesity, such as those in fat mass and obesity-associated (FTO) or melanocortin 4 receptor (MC4R) genes, among many others." (PMID 36289722, 2022). "We also acknowledge that obesity is polygenic in nature, while we only focused on MC4R in this study, which has a minor contribution to obesity." (PMID 35495128, 2022). "Two genetic knockout models of obesity were discussed, the melanocortin 4 receptor (MC4-R) and melanocortin 3 receptor (MC3-R) knockout mice." (PMID 35054972, 2022). "Obesity caused by mutations in POMC gene shows autosomal recessive inheritance, whereas those in MC4R are autosomal dominant." (PMID 36452324, 2022). "The melanocortin-4 receptor (MC4R) is critical for central satiety regulation, therefore presenting a potent target for pharmacological obesity treatment." (PMID 36362948, 2022). "Herein, we focused on four ORGs: fat mass and obesity-associated (FTO), melanocortin-4 receptor (MC4R), glucosamine-6-phosphate deaminase 2 (GNPDA2), and transmembrane protein 18 (TMEM18)." (PMID 36289871, 2022). "MC4R knockout mice progress obesity possibly as a result of reduced energy expenditure even in case of stable food intake." (PMID 35538513, 2022). "In the hypothalamus of mice with diet-induced obesity (DIO mice) there is neuronal injury and loss of abundance of melanocortin-4 receptor (MC4R), a GPCR that controls many body functions including energy and glucose homeostasis." (PMID 36614074, 2022). "Although the activation of MC4R produces satiety, which is interesting from the point of view of treating obesity, it also increases sympathetic activity and blood pressure, which limits the clinical use of MC4R agonists." (PMID 35742928, 2022). "Additional cilia genes that are associated with obesity include CEP19, CEP290, MC4R, ADCY 3, and RPGRIP1L." (PMID 36568981, 2022). "Clinical studies in patients with obesity have revealed that mutations in leptin, pro-opiomelanocortin (POMC), and melanocortin 4 receptor (MC4R) are positively associated with hyperphagia, hyperinsulinemia, and excessive adiposity." (PMID 35757435, 2022). "There was also a statistically significant difference between GLP-1 (p = 0.03) and cortisol levels (p = 0.002) in different genotypes of MC4R rs17782313 in individuals with obesity." (PMID 36123585, 2022). "Additional studies are needed by including the clinical level to clear up the biology of MC4R rs17782313 and its impact on the relationship between behavioral and hormonal factors and degree of obesity." (PMID 36123585, 2022). "To date, the administration of recombinant human leptin and the MC4R agonist setmelanotide are two genotype-informed therapies for rare monogenic obesity." (PMID 35574020, 2022). "A statistically significant difference was found between mean intake of energy and different genotypes of MC4R rs17782313 in individuals with obesity (p = 0.01) and all participants (p = 0.007)." (PMID 36123585, 2022). "Fat mass and obesity-associated (FTO) rs7185735 and melanocortin-4 receptor (MC4R) rs476828 variants were genotyped." (PMID 35845810, 2022).